MUTYH (mutY DNA glycosylase)
Diseases named in the same sentence as MUTYH in open-access papers (continued):
Sharing a sentence is not in itself a finding about the gene and the disease.
cancer (continued). "A further cancer (#22) acquired a homozygous deletion of the gastrointestinal cancer predisposition gene MUTYH and, in accordance with defective base excision repair, showed an ∼3-fold increase in the proportion of G:C>T:A SNVs in the post-treatment sample." (PMID 27045317, 2016). "We investigated cancer susceptibility associated with MUTYH inactivation in a mouse model of inflammation-dependent carcinogenesis induced by azoxymethane (AOM) and dextran sulphate (DSS)." (PMID 26109431, 2015). "SDHB, FGFR2 and MUTYH (AUC = 0.68, 0.67 and 0.65, respectively) were similarly associated with diverse cancer types and thus highly variable phenotypes." (PMID 23921638, 2013). "Inactivation of MUTYH has accordingly been associated with various cancer forms, including lung cancer, gastric cancer, CRC and recently also endometrial cancer." (PMID 19506731, 2008). "The MUTYH gene is recessive, and either two biallelic variants or one homozygous variant are required to inactivate its function; however, there are studies suggesting that monoallelic or heterozygous variants in the MUTYH gene may increase cancer risk." (PMID 40508121, 2025). "Moreover, mutations in MUTYH are increasingly associated with other types of cancer including extraintestinal cancers such as breast, ovary, bladder, thyroid and skin cancers." (PMID 40234396, 2025). "To provide insight into the impact of cancer associated variants (CAVs) and roles of the [4Fe-4S] cofactor in MUTYH function, we obtained the first crystal structure of human MUTYH in complex with DNA and defined structure-function relationships for 12 [4Fe-4S] associated CAVs." (PMID 40234396, 2025). "In these patients, the presence of cancer in individuals from both branches of the family strengthens the hypothesis that the MUTYH mutation is pathogenic itself, even when monoallelic." (PMID 41001951, 2025). "Interestingly, the heterozygous genotype behaved similarly to the parental, unedited HEK293T cells and the WT (null) line, which supports reports that MUTYH-associated cancers are autosomal recessive." (PMID 40156857, 2025). "In terms of clinical implications, rs3219489/MUTYH may serve as a genetic marker for cancer risk assessment, especially in specific populations, and could influence the effectiveness of radiochemotherapy in patients with non-small-cell lung cancer (NSCLC)." (PMID 40724862, 2025). "The second point, the relationship between MUTYH monoallelic variants and cancer predisposition, is much more controversial: three different studies so far concluded with a slightly increased risk of CRC in monoallelic carriers of MUTYH PVs though other researchers do not agree." (PMID 41001951, 2025). "Even though recent reports suggest that monoallelic variants in MUTYH may increase the risk for cancer, their clinical significance is still unclear, as sufficient information on the pathogenic mechanism is lacking." (PMID 38790183, 2024). "Notably, MUTYH is an example of a gene that plays a crucial role in genomic stability across all tissues affected by ROS damage, but mainly appears to modulate cancer risk in the colorectal epithelium." (PMID 39403956, 2024). "More research is needed to confirm the cancer risks linked to these heterozygous MUTYH mutations." (PMID 38136276, 2023). "Consistent with that observation, our study identified multiple MUTYH PVs and BVs in Neanderthals and Denisovans, highlighting that the extinct Neanderthals and Denisovans also contributed disease susceptibility, including cancer, to modern humans." (PMID 36979362, 2023). "Hence, the mutational processes resulting from defective MUTYH activity appear to promote the accumulation of putative cancer driver mutations in normal and neoplastic tissues." (PMID 35803914, 2022). "Here, the authors show that MUTYH mutations lead to an increased somatic base substitution mutation rate in normal intestinal epithelial cells, which is the likely cause for the increased cancer risk." (PMID 35803914, 2022).
cancer (continued). "Somatic MUTYH mutations are increasingly described in the literature and are noted to be present in 3.3% of all tumors curated by the Catalogue of Somatic Mutations in Cancer (COSMIC) database." (PMID 33419231, 2021). "Additionally, two heterozygous variants in autosomal recessive genes associated with cancer predisposition, were identified in MUTYH gene and XPC gene (each in 1 patient)." (PMID 31937788, 2020). "Of note, MUTYH is a recessive cancer predisposition gene, and cancer might arise if a person inherited another mutated allele." (PMID 32992489, 2020). "We found pathogenic/likely pathogenic variants in cancer-related genes that could contribute to the BC and TC phenotype (e.g., MUTYH c.1187G>A and SERPINA1 c.1096G>A)." (PMID 32443704, 2020). "Furthermore, some evidence has been reported about elevated cancer risk in monoallelic carriers and nowadays the associated cancer risks for MUTYH are controversial." (PMID 30675318, 2019). "The role of monoallelic MUTYH variants is still under debate, and while some studies have indicated an increased cancer risk for carriers of a single MUTYH variant, the p.Gly396Asp variant alone is unlikely to be the explanation for the MSI-H and/or IHC status of the tumors in our patients." (PMID 27300758, 2016). "Thus, a cancer-prone phenotype is always associated with MUTYH loss, independently from the contrasting toxicities induced by AOM/DSS or AZA/UVA exposures." (PMID 26109431, 2015). "Other authors assume that a slightly increased risk of cancer related to the presence of a monoallelic inactivation of MUTYH could be attributed to a situation of haploinsufficiency." (PMID 26511139, 2015). "However, OGG1 and/or MUTYH-deficient HAP1 cancer cells may have developed strategies to adjust to increased oxidative stress and maintain resistance to apoptosis which has recently been demonstrated for NEIL DNA glycosylases." (PMID 39662289, 2024). "Carriers of germline monoallelic MUTYH pathogenic variants, even when the second hit (e.g., LOH) did not occur, may present haploinsufficiency of the 8-oxoG and create C>A mutations in other tumor suppressors, which may explain an elevated rate of cancer in MUTYH-variant carriers." (PMID 39125905, 2024). "In our study, multiple MINAS patients developed cancer before the age of 50, and some exhibited tumor types associated with both mutated genes—such as the combination of BRCA1 and MUTYH, suggesting additive or synergistic effects." (PMID 41487526, 2025). "Lastly, isoTWAS identifies 52 genes (34 undetected by TWAS) that are associated with five or more cancer outcomes, including multiple known oncogenes or tumor suppressor genes, such as MYC, MUTYH, GNAI2, ACO2, and BMI1." (PMID 40775447, 2025). "Germline variants in MUTYH are associated with a distinctive mutational signature in CRC, characterized by an excess of G:C>T:A transversions, particularly affecting cancer driver genes such as APC and KRAS." (PMID 41001951, 2025). "Detecting heterozygous PVs in the MUTYH, NTHL1, MSH3, and MBD4 genes poses a clinical challenge for counseling monoallelic carriers about their cancer risk and for establishing rational surveillance protocols." (PMID 40237887, 2025). "A total of 75 index cases with CPs and a personal/family history of cancer were analyzed to identify genetic alterations in major hereditary polyposis-associated genes (APC, BMPR1A, MUTYH, PTEN, SMAD4, STK11)." (PMID 39518056, 2024). "Among the cancer-associated proteins we found five hotspot mutations conferring loss (NFE2L2 E79V/Q) or gain (PMS2 R107W, MUTYH S321L, CTNNB1 S33F) of interactions (Dataset EV6)." (PMID 39009827, 2024).
cancer (continued). "Similar signatures to our result were reported in patients with mutations of POLD1 and MUTYH, defective DNA MMR/BER, and with the habit of tobacco smoking producing reactive oxygen species in COSMIC catalog of somatic mutations in cancer (ver." (PMID 39159810, 2024). "In the non‐cancer cohort, 25/492 (5%) participants carried 17 unique P/LP variants in ATM, BRCA2, BRIP1, CHEK2, MUTYH, NBN, and PMS2 genes." (PMID 38308423, 2024). "Four (8%) were identified with variants in cancer predisposition genes, including two with APC (mild increased risk), and one each with BARD1 and MUTYH; the latter of which was previously identified in the family." (PMID 38256266, 2024). "Determination of the evolutionary origin of the variation is essential to understanding the etiological relationship between MUTYH variation and cancer development." (PMID 36979362, 2023). "Rare cancer-predisposing germline mutations of the DNA repair enzyme MUTYH have been associated with the ROS signature SBS18 and more frequent SGMs, supporting our findings of SBS18-driven SGMs in cancer genomes." (PMID 37922356, 2023). "For instance, higher levels of CHD1L, HDAC1, MUTYH, NEIL3, POLR2L, RUVBL1, and SPP1 expression in cancer cells have been linked to higher levels of drug resistance to nelarabine, acridine, chlorambucil, dexrazoxane, cladribine, and other drugs." (PMID 37923899, 2023). "Here we report the clinical and family cancer history of two siblings exhibiting colonic polyposis and harboring concurrent germline pathogenic variants in APC (c.1111G>T, p.Gly371∗) and MUTYH (c.536A>G, p.Tyr179Cys)." (PMID 37397536, 2023). "Eight patients harbored monoallelic variants in high/moderate penetrance cancer genes associated with autosomal dominant inheritance and a second variant in a gene associated with a recessive disorder (MUTYH, FANCA, NTHL1) or low penetrance cancer (TYR)." (PMID 36132150, 2022). "Statistically, the most significant differences in the frequency of P/LP germline variants between patients and population-matched non-cancer controls were detected in PMS2, DNAJC21 (truncating variants only), and MUTYH (OR ranging from 4.1 to 48.9)." (PMID 35739278, 2022). "PV were detected in 13 cancer predisposition genes including ATM (n=4), BLM (n=1), BRCA1 (n=1), BRCA2 (n=7), BRIP1 (n=1), CDKN2A (n=1), CHEK2 (n=9), FANCC (n=1), MUTYH (n=10), NBN (n=1), PALB2 (n=1), RAD51D (n=1) and STK11 (n=1)." (PMID 36091166, 2022). "For instance, STK11 (20.59% v 5.95%, odds ratio [OR] = 4.10), KEAP1 (15.38% v 4.61%, OR = 3.76), and MUTYH (4.96% v 2.35%, OR = 2.17) were more frequently mutated in KRASG12C-mutant tumors across all cancer types (P < .001 and FDR-P < .01 for all comparisons)." (PMID 35319967, 2022). "Here we demonstrate the coinheritance of monoallelic variants in MSH6 and MUTYH consistent with cosegregation with CRC, further supporting a role for digenic inheritance in cancer predisposition." (PMID 32615015, 2020). "Here, we demonstrate, for the first time, the coinheritance of monoallelic variants in MSH6 and MUTYH consistent with the cosegregation with CRC, further supporting a role for digenic inheritance in cancer predisposition." (PMID 32615015, 2020). "Pathogenic variants were identified in CHEK2, MUTYH, and RAD51B in four cancer patients, which represented 8.3% of the cohort." (PMID 31780696, 2019). "Instead, most were in moderate-penetrance genes that confer a two- to four-fold increase in cancer risk (eg, ATM and CHEK2) as well as low-penetrance mutations (eg, monoallelic MUTYH and APC I1307K)." (PMID 34322651, 2019).
cancer (continued). "Polymorphisms of MLH1, APEX1, MUTYH, OGG1, NUDT1, and XRCC5 are associated with sporadic CRC and other site‐specific cancers." (PMID 29664240, 2018). "The most commonly mutated cancer susceptibility genes were BRCA2 (n = 31), BRCA1 (n = 22), ATM (n = 19), and MUTYH (n = 19)." (PMID 29684080, 2018). "In particular, the UC-associated tumors display both an accumulation of 8-oxoG and an altered expression of MUTYH protein in cancer cells." (PMID 22876359, 2012). "While the strong impact of biallelic MUTYH mutations on CRC risk has been demonstrated, the cancer risk associated with germline monoallelic mutations is still controversial." (PMID 22876359, 2012). "All five patients, who had findings in cancer predisposition genes (MLH1 & MUTYH), did not report familial cancer cases, typically associated with findings in these genes." (PMID 40403485, 2025). "Good responses have also been observed in MUTYH- and MBD4-deficient cancers." (PMID 40237887, 2025). "Monoallelic carriers of MUTYH pathogenic variants are not at increased risk for cancer, and it is known that roughly 1%–2% of people of European ancestry carry a monoallelic MUTYH pathogenic variant." (PMID 39907309, 2025). "Of the 71 patients with CFTR PVs, two patients had PV in other genes with either an established or possible association with increased cancer risk consisting of the L2357 frameshift variant in BRCA2 (rs80359636) and the Y179C missense variant in MUTYH (rs34612342)." (PMID 41147257, 2025). "Ironically, the “Achilles heel” of MUTYH may be its [4Fe-4S] cluster that could be targeted in cancer cells that have become reliant on MUTYH to survive." (PMID 40234396, 2025). "Among the younger group, 53 had BRCA1/2 germline PVs/LPVs (38%), 15 were carriers of other cancer susceptibility genes (10%), primarily APC, NBN, ATM, MUTYH, MLH1, and only 2 patients were carriers of PVs/LPVs in both BRCA1/2 and other susceptibility genes (1%)." (PMID 38136276, 2023). "The median age for cancer diagnosis across the BRCA1/2 mutation carriers was 46 years, in the CHEK2 group it was 42.5 years, 44.8 years for ATM, 48.6 years for PALB2, 44 years for MUTYH, and 45.6 years for BLM." (PMID 38201513, 2023). "Indeed, the AF of MUTYH c.934–2 A > G in non-cancer individuals from the Genome Aggregation Database (GAD) was only 0.11% (allele count (AC): 312 of 28,2820) in line with this annotation." (PMID 35273153, 2022). "Together these observations indicate that oxidative DNA damage due to MUTYH inactivation may contribute to cancer etiology in several organs." (PMID 33917078, 2021). "For instance, double knockout mice lacking both OGG1 and MUTYH (MutY homolog) are highly susceptible to cancer and have shortened life spans." (PMID 33925271, 2021). "7/13 had pathogenic heterozygous mutations in MUTYH which are not thought to be causative of the probands’ cancers and therefore believed to be incidental findings with limited clinical relevance." (PMID 30875412, 2019). "At present there is little information about the role of MUTYH in other types of cancer." (PMID 30886832, 2019). "Moreover, clarifying the role of monoallelic MUTYH PVs in tumor development could inform targeted cancer prevention strategies for healthy carriers." (PMID 41001951, 2025). "Therefore, this study would support a nonpathogenic role for monoallelic MUTYH variants in cancer pathogenesis." (PMID 38790183, 2024). "Whether individual occurrences of biallelic MUTYH in our cohort represent causal relationships between MUTYH-related base excision repair deficiency (BER) and the diagnosed cancer type versus unveiling unrelated, previously unrecognized hereditary risk is unclear." (PMID 37568048, 2023).
cancer (continued). "The fact that biallelic MUTYH mutations were found more commonly among individuals not meeting Medicare criteria may be due to less family history of cancer among autosomal recessive conditions." (PMID 34585040, 2021). "Whether or not individuals who are heterozygous for MUTYH mutations may be at risk for cancer is debated." (PMID 29371908, 2018). "However, similar exclusion of families carrying APC, MUTYH or POLE and POLD1 mutations because known cancers other than CRC are rare or unknown in these syndrome, and exclusion based on CRC would have defeated the purpose." (PMID 28701784, 2017). "The strong association between lack of DNA repair, genetic instability and cancer is dramatically demonstrated by a number of cancer-prone human syndromes, such as xeroderma pigmentosum, ataxia-telangiectasia, Fanconi anemia, Hereditary Nonpolyposis Colorectal Cancer and MUTYH-Associated Polyposis." (PMID 23066388, 2012). "Current gene- and disease-informed specifications are under development for the MUTYH, POLE and POLD1 genes, and other adenomatous and hamartomatous polyposis genes will follow to optimize clinical management and opportunities for cancer prevention." (PMID 40237887, 2025). "In particular, genetic testing revealed that four of these patients (families 15, 16, 19, and 20) who had a personal and family history of CPs and cancer harbored four different germline VUSs involving adenomatous polyposis genes (APC and MUTYH)." (PMID 39518056, 2024). "The most common genes in which PPGVs were identified pan-cancer were BRCA2 (16.9% of PPGVs), MUTYH (15.0%), ATM (13.4%), CHEK2 (11.7%), and BRCA1 (9.8%)." (PMID 37568048, 2023). "Presented interactions between Sirt3 and MUTYH, NEIL1, and APE1 in cancer cells and the effect of Sirt3 on the cellular response to oxidative stress indicate the necessity of Sirt3 for proper cell antioxidative reaction." (PMID 35440893, 2022). "Specifically, MUTYH and BIRC3 are both established as cancer drivers, and they both appear in clinical panels." (PMID 34290314, 2021). "Twenty‐two rare variants were shared by the three patients, including variants in the MSH6 (NM_000179.2: c.3299C > T, p.Thr1100Met) and MUTYH (NM_001128425.1: c.536A > G, p.Tyr179Cys) genes, while the other 20 genes could not be clearly linked to cancer predisposition." (PMID 32615015, 2020). "Studies have shown changes in the expression of MUTYH, KLF6, KLF4 and WNT1 genes in various cancers." (PMID 31724937, 2019). "Gene expression data also delineated that MUTYH gene could play a physiological role in crosstalk between ErbB and BER pathways and this function is instead lost in cancer cells." (PMID 35269445, 2022). "We identified genes for which ASEs were observed in both the Afro-Caribbean cohort and the Jurkat cells expressing Tax or HBZ, including cancer genes EIF4A2, IKBKB, LZTR1, STAT6 (for Tax); CARS, MDM2, IKZF1 (for HBZ); and EWSR1, MUTYH, and PTPRC (for both Tax and HBZ)." (PMID 34543356, 2021). "Next to MSH6 and MUTYH, CUX1 has been described as a cancer‐driving gene." (PMID 32615015, 2020).